SNORD113-7 (small nucleolar RNA, C/D box 113-7)
Synonyms: 14q(I-7)
Gene: Small nucleolar RNA gene on chromosome 14 (100,941,126 to 100,941,202, forward strand). Ensembl gene ENSG00000200632.
Gene Ontology:
Biological process: RNA processing
Cellular component: nucleolus
Homologues: Orthologues: chimpanzee SNORD113-7 (99% identical), macaque SNORD113-7 (99% identical), guinea pig SNORD113-7 (87% identical), pig SNORD113-7 (87% identical). Paralogues in human: SNORD113-5 (78% identical), SNORD113-3 (77% identical), SNORD113-8 (77% identical), SNORD113-6 (73% identical), SNORD113-9 (73% identical), SNORD113-4 (71% identical), SNORD114-6 (71% identical), SNORD114-15 (70% identical), SNORD114-21 (70% identical), SNORD114-22 (70% identical), SNORD114-23 (70% identical), SNORD114-26 (70% identical), and 26 more.